CHI3L1 (chitinase 3 like 1)
Diseases named in the same sentence as CHI3L1 in open-access papers (continued):
Sharing a sentence is not in itself a finding about the gene and the disease.
Cognitive impairment (44 papers, 2015 to 2026). Abnormal cognition is characterized by deficits in thinking, reasoning, or remembering. "Although the internalization of membrane NMDARs induced by anti‐NMDAR antibodies has been shown to be reversible, the mechanisms underlying antibody‐induced cognitive impairment, as well as the potential involvement of CHI3L1, remain largely unclear." (PMID 41489316, 2026). "In multivariable logistic models, serum CHI3L1 (OR: 2.57, 95% CI 1.38–5.47, p = 0.006) and CSF CHI3L1 (OR: 4.28, 95% CI 1.97–11.49, p = 0.001) levels remained independently associated with cognitive impairment." (PMID 41489316, 2026). "The disruption of white matter macrostructure and microstructure is significantly associated with increased Chi3l1 levels, whereas white matter damage can mediate the associations between increased serum Chi3l1 levels and cognitive impairment." (PMID 39769202, 2024). "It concluded that higher levels of CHI3L1 in serum were associated with more severe cognitive impairment and more disease progression." (PMID 36988727, 2023). "CHI3L1, a marker of inflammation and neurodegeneration, has been implicated in the pathophysiology of cognitive impairment in MS." (PMID 36988727, 2023). "White matter CHI3L1 inflammatory response is associated with cognitive impairment early in the onset of AD." (PMID 32066474, 2020). "Elevated CSF CHI3L1 levels have been linked to cognitive impairments in the early stages of MS." (PMID 39827337, 2025). "Elevated CSF levels of chitinase-3-like-1 (CHI3L1) have been linked to cognitive impairments in early MS, and the progression to clinically definite MS, as well as disease progression in general; CHI3L1 has been shown to activate microglia and macrophages, thereby indirectly promoting demyelination." (PMID 40443664, 2025). "Our study showed significant cognitive impairment associated with higher levels of CSF CHI3L1." (PMID 36988727, 2023). "Moreover, elevated CHI3L1 levels were closely associated with long‐term cognitive impairment." (PMID 41489316, 2026). "The increase of CHI3L1 was also associated with cognitive dysfunction, and CHI3L1 plays a significant role in white matter neuroinflammation associated with cognitive decline in AD patients, which suggests that white matter CHI3L1 relates to cognitive impairment in the early onset of AD." (PMID 38667293, 2024). "Serum CHI3L1 levels correlate with neurofilament light chain and cognitive impairment measured by the Mini‐Mental State Examination (MMSE)." (PMID 40495463, 2025). "In this exploratory study, we investigated peripheral CHI3L1 mRNA expression in biomarker-confirmed individuals with AD, mild cognitive impairment (MCI), and cognitively healthy controls (HC)." (PMID 41425914, 2025). "We analyzed peripheral blood CHI3L1 mRNA expression in a well-characterized cohort comprising individuals with biomarker-confirmed AD (n = 34), mild cognitive impairment (MCI; n = 31), and cognitively healthy controls (HC; n = 21)." (PMID 41425914, 2025). "Our study provides compelling evidence that targeting CHI3L1 with a monoclonal antibody (H1) mitigates key pathological features of AD in Tg2576 mouse, including neuroinflammation, amyloid deposition, and cognitive impairment." (PMID 41573517, 2025). "Taken together, there was significantly less impairment of Aβ-induced cognitive impairment in CHI3L1 KO mice compared to WT mice." (PMID 38791588, 2024). "Chitinase 3-like 1 (CHI3L1) is a glycoprotein secreted by activated glia, whose increment has been related to disease progression, cognitive impairment, and disability." (PMID 36114980, 2023). "The severity of cognitive impairment (either MMSE or BICAMS) showed significant good positive correlation with CSF CHI3L1 level (p = 0.001, r = 0.670, 0.563 consecutively)." (PMID 36988727, 2023). "Our results suggest that S CHI3L1 reflects the severity of cognitive deficits assessed by MMSE." (PMID 40495463, 2025).
Cognitive impairment (continued). "Astrocyte‐specific CHI3L1 deletion restores neurogenesis and ameliorates cognitive deficits." (PMID 40859959, 2025). "Our previous study demonstrated that 2-({3-[2-(1-Cyclohexen-1-yl)ethyl]-6,7-dimethoxy-4-oxo-3,4-dihydro-2-quinazolinyl}culfanyl)-N-(4-ethylphenyl)butanamide, a CHI3L1 inhibiting compound, alleviates memory and cognitive impairment and inhibits neuroinflammation in AD mouse models." (PMID 38791588, 2024). "CHI3L1 (also known as YKL40) is of particular interest due to emerging evidence highlighting its role in neuroinflammatory astrocytic mechanisms, including the impairment of neurogenesis and the development of cognitive impairment." (PMID 39154174, 2024). "Accumulating research has shown that Chi3l1 levels are greater in patients with early AD (407.81 ± 73.25 ng/mL) than in controls (96.91 ± 11.02 ng/mL) or patients with mild cognitive impairment (MCI; 176.49 ± 25.68 ng/mL), making it a potential biomarker for preclinical AD." (PMID 39769202, 2024). "Overall, these studies suggest that CSF CHI3L1 levels may be a useful biomarker for predicting cognitive impairment severity in MS, particularly in the domains of information processing speed, working memory, verbal memory, and attention." (PMID 36988727, 2023). "Recent studies have suggested that CSF biomarkers, such as CHI3L1, may be useful in predicting cognitive impairment in MS." (PMID 36988727, 2023). "The CSF level of CHI3L1 was correlated to cognitive impairment in the early stages of MS." (PMID 38062768, 2023). "Because AMPAR function is highly related to long-term potentiation (LTP), future studies should investigate whether YKL-40/Chi3l1-induced AMPAR dysfunction and cognitive impairment are associated with altered LTP function." (PMID 38042775, 2023). "CHI3L1 found in the cerebral spinal fluid (CSF) obtained from preclinical and prodromal cases of AD has been suggested as a biomarker for discerning cognitively normal from mild cognitive impairment (MCI) individuals." (PMID 32066474, 2020). "Multiple studies investigate the relation between CSF concentration of chitinase-3-like-1 proteins and cognitive impairment which seems to imply that glial activation which is involved in atrophic changes of the brain and axonal loss may negatively influence different cognitive domains." (PMID 36988727, 2023). "In addition, we aimed to study the relationship between the level of CHI3L1 in CSF and the clinical disability parameters in MS, including cognitive impairment with the aim of determining whether CHI3L1 could be used as a biomarker for MS progression." (PMID 36988727, 2023). "Astrocyte‐derived CHI3L1 is elevated in both a mouse model and pediatric patients with anti‐NMDAR encephalitis, coinciding with impaired hippocampal neurogenesis and cognitive deficits." (PMID 41489316, 2026). "Nonetheless, these findings emphasize CHI3L1’s role in HIV-related neurodegeneration and its potential for therapeutic strategies aimed at alleviating cognitive deficits in HIV-infected individuals." (PMID 39827337, 2025). "CHI3L1 (protein YKL‐40/chitinase‐3‐like protein 1), an astrocyte‐derived protein, is elevated in AD CSF and discussed as a marker for progression from mild cognitive impairment to AD." (PMID 32485097, 2020). "Patients with anti-LGI1 encephalitis presenting with cognitive impairments (n = 18) had significantly higher CSF CHI3L1 levels than those without cognitive impairment symptoms (n = 12, p = 0.022), but these two groups had similar serum CHI3L1 levels." (PMID 36685530, 2022). "Exploratory correlations with CRP and circulating lipids did not indicate substantial metabolic inflammation effects in controls or mild cognitive impairment (MCI), suggesting that the EOAD/ε4-linked CHI3L1 signal is not driven by general systemic inflammation." (PMID 41425914, 2025).
Cognitive impairment (continued). "Additionally, in autoimmune brain diseases such as neuromyelitis optica (NMO), Chi3l1 reportedly impairs hippocampal neurogenesis and cognitive function, whereas blocking the Chi3l1/CRTH2/β-catenin cascade contributes to restoring neurogenesis and improving cognitive deficits." (PMID 39769202, 2024). "Additionally, patients presenting with cognitive impairment had significantly higher CSF CHI3L1 levels and mRS scores than those without cognitive impairment symptoms." (PMID 36685530, 2022). "Moreover, CSF CHI3L1 levels were higher in anti-LGI1 encephalitis patients presenting with cognitive impairment than those without cognitive impairment symptoms." (PMID 36685530, 2022). "Interestingly, cortical CD44 was reported in a subset of astrocytes in FC layers I–II and WM in humans without cognitive impairment, similar to the CHI3L1 distribution observed in the present NCI cases." (PMID 32066474, 2020).
Hypertension (44 papers, 2009 to 2026). The presence of chronic increased pressure in the systemic arterial system. "The text-mining score of CHI3L1 in hypertension was 0.854, which represented the highest association among the CVDs." (PMID 38177294, 2024). "Several studies have demonstrated that CHI3L1 is associated with the severity of hypertension, insulin-resistant hypertension, portal hypertension, and several heart disease-related hypertension." (PMID 38177294, 2024). "Hypertension patients exhibit high Chi3l1 levels, which have been demonstrated to be associated with increased arterial stiffness, modifiable risk factors for CVD, major cardiovascular outcomes, endothelial dysfunction, and inflammation." (PMID 39769202, 2024). "In the present study, we aimed to examine the association of tag SNPs in CHI3L1 gene with YKL‐40 levels and the incidence of hypertension in a population‐based nested case‐control study in China." (PMID 33280245, 2021). "Differential transcription of four of these DEGs, which are known as associated with hypertension (F2r, Chi3l1, Ephx2, and Tlr3), was validated by qPCR." (PMID 32039698, 2019). "One of these genes, chitinase 3-like 1 (cartilage glycoprotein-39) (Chi3l1), is known to be associated with hypertension." (PMID 26822062, 2016). "CHI3L1 was reported to be associated with the risk of hypertension." (PMID 38177294, 2024). "Moreover, the rs10399805, rs4950928 and rs2297839 genotypes in the CHI3L1 gene were identified as stable biomarkers for predicting a hypertension risk." (PMID 37902124, 2023). "It is also reported that plasm CHI3L1 levels are associated with hypertension in patients with OSA." (PMID 35280860, 2022). "Our present study is the first one to detect the association between the CHI3L1 SNPs and the risk of hypertension based on a nested case‐control study with a median follow‐up of five years, which considerably reduces potential biases inherent in cross‐sectional or retrospective studies." (PMID 33280245, 2021). "Whether the variants of CHI3L1 gene were associated with both YKL‐40 levels and hypertension needs to be further elucidated." (PMID 33280245, 2021). "Reportedly, the genetic variant for rs10399805 is associated with higher Chi3l1 levels, whereas the genetic variants for rs2297839 and rs4950928 have lower Chi3l1 levels; however, all three SNPs of Chi3l1 could significantly improve the accuracy of risk prediction for hypertension." (PMID 39769202, 2024). "Elevated circulating CHI3L1 levels are associated with hypertension in obstructive sleep apnea patients and cirrhotic portal hypertension (CPH), indicating the potential of CHI3L1 as a specific biomarker for hypertension." (PMID 38177294, 2024). "STING analysis revealed that the following proteins were related to CHI3L1 in hypertension: VEGFA, IGF1, IL-13, IL-6, CRP, STAT3, TNF and CST2." (PMID 38177294, 2024). "In a study with 60 essential hypertension patients and 30 healthy subjects, serum CHI3L1 levels were significantly higher in the essential hypertension group than in the control group [51.7 (35.6–341.9) μg/L vs. 33.2 (23.3–167.3) μg/L]." (PMID 38177294, 2024). "When the COVID-19– and COVID-19+ ED patients were evaluated together, the levels of circulating CHI3L1 were increased in the patients who were older than 50 years of age and/or had hypertension." (PMID 34747367, 2021). "Overall, these studies demonstrate that the levels of circulating CHI3L1 are increased in the elderly and patients with comorbid disease like hypertension." (PMID 34747367, 2021). "In accord with what has been reported in the literature, when the ED cohort patients were evaluated as a group, the levels of circulating CHI3L1 were increased in patients who were elderly, had hypertension, had comorbid diseases, or required hospitalization." (PMID 34747367, 2021). "Further studies regarding the drug target of CHI3L1 in hypertension are needed." (PMID 38177294, 2024).
Hypertension (continued). "Importantly, within the COVID-19+ ED patients, the levels of circulating CHI3L1 were statistically increased in the patients who were elderly, had hypertension or other comorbid diseases, and/or required hospitalization." (PMID 34747367, 2021). "Hence, this study investigated whether the associations between astrocyte reactivity, measured by cerebrospinal fluid (CSF), Chitinase 3-like protein 1 (CHI3L1/YKL-40), and AD-related pathologies were mediated by neuroinflammation and whether these associations were modified by hypertension." (PMID 40842648, 2025). "According to a nested case-control study in China, Chi3l1 is correlated with hypertension incidence only among men but not women, and it also predicts the risk of developing hypertension in the prehypertensive population." (PMID 39769202, 2024).
lung carcinoma (44 papers, 2010 to 2026). "Meta-analyses further support these finding, showing that high CHI3L1 expression is significantly associated with reduced overall survival in lung cancer patients." (PMID 40643503, 2025). "In models of colon and lung cancer, CHI3L1 overexpression correlates with increased tumor size and number, whereas CHI3L1 deficiency markedly suppresses tumor formation." (PMID 40643503, 2025). "Lower panel: In lung cancer, elevated CHI3L1 levels are linked to increased VEGF expression, promoting angiogenesis and tumor progression." (PMID 38177294, 2024). "High serum levels of CHI3L1 are associated with poorer prognosis and decreased overall survival for various cancers, including lung cancer." (PMID 37374908, 2023). "Our previous analysis with GWAS/OMIM/DEG program confirmed the significant association between CHI3L1 and lung cancer development." (PMID 34758182, 2022). "Gene–disease and gene–gene network analyses indicated that CHI3L1 and IL‐13Rα2 are commonly associated with many diseases including lung cancer and these genes are colocalized." (PMID 34758182, 2022). "Ebractenoid F has an anti-lung cancer effect, although the exact mechanisms by which it affects CHI3L1 and CHI3L1-associated signaling are yet to be elucidated." (PMID 36615523, 2022). "In our previous study, we also found that CHI3L1 is markedly associated with the development of lung cancer." (PMID 36615523, 2022). "CHI3L1 is overexpressed in lung cancer and tumor-associated macrophages, and its high expression is detected in the serum of metastatic lung cancer patients." (PMID 36615523, 2022). "These ELISA data implicated that an increase in plasma CHI3L1 level during immunotherapy was associated with poor response to treatment in lung cancer patients." (PMID 34987649, 2022). "For instance, in lung cancer mouse model CHI3L1-deficient T cells are prone to differentiating into Th1 cells with enhanced anti-tumor activity." (PMID 34612767, 2021). "To determine whether CHI3L1 is actually a viable candidate therapeutic approach (as a potential drug target) in lung cancer, we examined the association between CHI3L1 and lung cancer using the Open Targets Platform." (PMID 38177294, 2024). "Proteins were classified based on this approach to identify proteins associated with CHI3L1 in lung cancer, which could suggest potential target proteins that are functionally related to CHI3L1." (PMID 38177294, 2024). "This study examined the association between CHI3L1 and autophagy in human lung cancer cells." (PMID 37340009, 2023). "Moreover, our previous study involving big data analysis and experiments with shRNA of CHI3L1 showed that CHI3L1 is associated with the development of several cancers, especially lung cancer." (PMID 34758182, 2022). "Next, we further studied whether plasma level of CHI3L1 was associated with therapeutic efficacy of α-PD-1 treatment in lung cancer patients." (PMID 34987649, 2022). "Together, these clinical results demonstrated for the first time that tumors from advanced lung cancer patients with poor survival was characterized by a distinct immunosuppressive TME with a high level of stromal CHI3L1+Rab37+ associated with tumor infiltrating M2 macrophages." (PMID 34987649, 2022). "Based on these results, ebractenoid F may inhibit the growth of lung cancer cells through inhibition of the AKT pathway associated with CHI3L1 signaling." (PMID 36615523, 2022). "Thus, our data demonstrate that ebractenoid F may serve as a potential anti-lung cancer compound targeting CHI3L1-associated AKT signaling." (PMID 36615523, 2022).